MYC (MYC proto-oncogene, bHLH transcription factor)
Diseases named in the same sentence as MYC in open-access papers (continued):
Sharing a sentence is not in itself a finding about the gene and the disease.
prostate carcinoma (continued). "ZFHX3 inhibits the proliferation of prostate cancer cells by downregulating MYC gene expression." (PMID 33933102, 2021). "To clarify, whether the expression of c-Myc is associated with IKKα expression in vivo, we investigated a well-established transgene mouse model of prostate cancer, where c-Myc is overexpressed specifically in prostate epithelium (Hi-MYC mouse)." (PMID 33461590, 2021). "However, it has been recently demonstrated that there is an inverse relationship between MYC activity in prostatic cancer, which drives prostate cancer progression, and MEIS1 expression." (PMID 34698191, 2021). "Knockdown of PVT1 down-regulates the level of MYC protein in prostate cancer cell lines." (PMID 34940755, 2021). "KDM1A inhibition by HCI-2509 downregulates MYC expression in prostate cancer cells, suggesting that it may act as a promising therapeutic in castration- and docetaxel-resistant prostate cancer." (PMID 33801599, 2021). "Another study demonstrated that knockdown of VIRMA could decrease the stability of CCAT1 and CCAT2 lncRNA in an m6A-dependent manner to regulate MYC transcription, promoting progression of prostate cancer." (PMID 33731118, 2021). "In addition, clinical samples from prostate cancer patients stratified by saturated fat intake reveal enrichment of a MYC target gene signature and greater overall mortality in those consuming high amounts of saturated fat." (PMID 34109280, 2021). "N-MYC and c-MYC are well-studied drivers of neuroendocrine plasticity in prostate cancer." (PMID 34298815, 2021). "Repeating this analysis with a prostate cancer-specific gene set generated by MYC overexpression in LNCaP cells, PRAD correlation with proliferation increased modestly (r = 0.5609, 95% C.I. 0.4972–0.6186, P < 0.0001), but was still below the median correlation coefficient." (PMID 32681068, 2020). "In the balanced differentiated group of young and old prostate cancer patients, MYC and HDAC1 genes were emerged as a central node and uniquely upregulated in young men whereas VEGFA is the key node in old men and found to be down regulated along with HLA and ANXA2 genes in old patients." (PMID 33575208, 2020). "Further, we tested whether the alterations in these lncRNAs and MYC have any effect on the survival of the prostate cancer patients." (PMID 32680982, 2020). "As MYC is commonly overexpressed in prostate cancer where it is recognized as an early driver of carcinogenesis, this raises the question of whether upregulation of ABCC1 might be regulated by c-MYC in prostate cancer cells." (PMID 32718079, 2020). "Interestingly, transcription of low copy transcripts in the region arising from −400 to +120 of the MYC TSS was reported in prostate cancer cells." (PMID 32722129, 2020). "Interestingly, the PI3K-AKT-mTOR, WNT, MAPK and AR signaling cascades all converge to regulate the transcription factor MYC, which is frequently amplified in prostate cancer/mCRPC." (PMID 32630372, 2020). "All prostate cancer cell lines used in this study express c-MYC, consistent with previous data." (PMID 32718079, 2020). "MYC represents another gene frequently overexpressed in many tumors, and its role in promoting metabolic reprogramming has been reported in several cancer types, including colorectal, pancreatic, breast, prostate cancer, and glioma." (PMID 32932943, 2020). "Moreover, in prostate cancer, MYC activity was correlated with dysregulation of the PI3K/AKT/mTOR pathway, which induced cellular survival." (PMID 32933107, 2020). "Moreover, as our analysis shows, the MYC downregulation can be due to let-7c upregulation in this cell line as well, which was described previously in prostate cancer cells." (PMID 32283808, 2020). "FOXM1 was also identified as the downstream target of MYC in prostate cancer." (PMID 32210076, 2020).
prostate carcinoma (continued). "Because MYC and AR signaling are essential for prostate cancer initiation, MYC may be another key determinant both of BET bromodomain inhibitor and LSD1 inhibitor sensitivity in PCa." (PMID 31901895, 2020). "Among the 89 prostate cancer patients from the University of Maryland Medical Center who had available MYC DNA methylation data for analysis, age at radical prostatectomy ranged from 42–75 years, with a median age of 58 years; the distribution of age at diagnosis was similar to the age at surgery." (PMID 33374332, 2020). "MYC overexpression is an early event in prostate cancer development." (PMID 33255593, 2020). "Additional work, however, is required to definitely establish whether c-MYC regulates ABCC1 protein levels in prostate cancer cells." (PMID 32718079, 2020). "Additionally, both overexpression of miR-449a and knockdown of c-MYC sensitized prostate cancer cells to IR and miR-449a also enhanced radiosensitivity in xenograft models." (PMID 32585857, 2020). "Direct binding of ZFHX3 to MYC promoter has also been detected in prostate cancer cells." (PMID 33217982, 2020). "Inhibition of c-MYC by miR-449a resulted in IR-induced G2/M arrest in prostate cancer cells." (PMID 32585857, 2020). "Finally, we show that the saturated fat-induced MYC transcriptional signature is not only a tumour biomarker for the patients’ diet, but it is prognostic for progression to metastatic, lethal prostate cancer." (PMID 31554818, 2019). "Recent research elucidated to the functional importance of this region in regulating MYC expression in prostate cancer, which could highlight a putative role of this somatically acquired amplification." (PMID 31748536, 2019). "The SFI-induced MYC signature independently predicts prostate cancer progression and death." (PMID 31554818, 2019). "Therefore, MYC upregulation plays a causal role in the promotion of cell proliferation and colony formation by the loss of ZFHX3 in prostate cancer cells." (PMID 30979864, 2019). "Indeed, the SFI-induced MYC signature is able to predict prostate cancer lethality, independently of the degree of tumour differentiation and patient obesity status and the robustness of this finding was validated in four independent cohorts." (PMID 31554818, 2019). "According to these findings it was suggested that MYC hyperexpression could play a relevant role in prostate cancer initiation." (PMID 31366128, 2019). "MYC promotes metastasis in established animal models of lung and prostate cancer." (PMID 30866868, 2019). "POM121 regulates nuclear import of oncogenic MYC through importinβ to promote prostate cancer." (PMID 31528211, 2019). "Additionally, the inhibitory effect of PGG on MYC expression can also be observed in prostate cancer and leukemia cell lines." (PMID 30760754, 2019). "Few studies have explored the mechanisms responsible for MYC activation in prostate cancer cells." (PMID 31366128, 2019). "Importantly, treatment with the CRBN-mediated degraders on prostate cancer cells induces a pronounced inhibitory effect on both AR and MYC signaling axes and elicited a markedly inhibitory effect on cell growth and stimulatory on cell apoptosis." (PMID 31366128, 2019). "The oncogene c-MYC (MYC) is a key driver of human prostate cancer tumorigenesis and progression." (PMID 31554818, 2019). "Thus, while MYC plays an oncogenic role in prostate cancer, our results support a tumor suppressive function for miR-27a-5p in this cancer model." (PMID 29415999, 2018). "To test if CP1 could invade prostate cancer cells, we repeated this in vitro gentamicin protection assay with the MYC-driven murine prostate cancer cell line, Myc-CaP21." (PMID 29686284, 2018).
prostate carcinoma (continued). "Upregulation of MYC and miRNAs deregulation are common in prostate cancer (PCa)." (PMID 29415999, 2018). "Moreover, MYC upregulation is an early event in human prostate cancer, and MYC overexpression is sufficient to transform luminal epithelial cells into pre-malignant derivatives in the mouse prostatic gland." (PMID 30619451, 2018). "The treatment of C4-2 prostate cancer cells (more invasive derivative of LNCaP cells and with comparatively lower expression of PrKD1) with MYC inhibitor increased the transcriptional expression of PrKD1 confirming the negative regulatory role of MYC on PrKD1 expression." (PMID 29108267, 2017). "While additional studies are needed to prove the feasibility and efficacy of targeting in prostate cancer, it is conceivable that targeting the transcriptional regulators such as MYC/MAX could selectively and indirectly increase the PrKD1 expression in cells." (PMID 29108267, 2017). "Wedelolactone has been reported downregulates the expression of MYC mRNA in prostate cancer cells." (PMID 29142311, 2017). "In prostate cancer mouse models expressing high levels of MYC, treatment with metformin has been shown to decrease MYC levels both in vivo and in vitro, inhibiting the growth of prostate cancer cells while minimally inhibiting growth of normal prostatic epithelial cells." (PMID 28362357, 2017). "Furthermore, a recent study has provided preclinical evidence demonstrating improved therapeutic efficacy in preclinical models of MYC-driven prostate cancer upon combined treatment of CX-5461 and an inhibitor of PIM kinase." (PMID 28117679, 2017). "In addition, this combination showed significant efficacy in an aggressive chemotherapy-refractory high MYC patient-derived xenograft (PDX) model of prostate cancer." (PMID 28117679, 2017). "Moreover, the small-molecule MYC inhibitor, 10058-F4, was reported to be effective in anti-tumor treatment, such as for leukemia, prostate cancer, and hepatocellular carcinoma." (PMID 28590415, 2017). "For example, STAT3, AP1, AR, ERG, EGR1 and MYC are important TFs that are responsible for the progression of prostate cancer by affecting a wide variety of pathways involved in cell proliferation and differentiation, apoptosis, tumor suppressing and various cell signaling pathway." (PMID 28005952, 2016). "This could be achieved by overexpressing a FBXW7-resistant MYC mutant (T58A) in prostate cancer cells, and treating these cells with GUTK during cell cycle re-entry." (PMID 27253416, 2016). "Overexpression of EGR1, GDF15 and MYC in prostate cancer was previously reported in the literature." (PMID 28005952, 2016). "We examined SIRT3's role on the degradation and ubiquitination of c-MYC in prostate cancer." (PMID 26317998, 2015). "Furthermore, POX expression is inhibited by MYC via miR-23b* in lymphoma, renal, and prostate cancers." (PMID 25621173, 2015). "Furthermore, c-MYC is found to be up-regulated in prostate cancer and highly correlated with the progression of the disease." (PMID 26317998, 2015).
prostate carcinoma (continued). "Given the broad spectrum of pathways regulated by PP2A it is feasible that those prostate cancers driven by MYC and AR may also benefit from therapies targeting endogenous regulators of PP2A." (PMID 26563471, 2015). "It is reported that prostate cancers driven by oncogene MYC (v-myc avian myelocytomatosis viral oncogene homolog) in mice and human showed a reduced level of H3K27me3, and siRNA knockdown of MYC results in increased levels of H3K27me3 in prostate cancer cell lines." (PMID 25606572, 2014). "The copy number gain of genes in chromosomal region 8q21-24 has been demonstrated to be associated with genesis and progression of prostate cancer (PCa) with a significant amplification of E2F5 and MYC genes, the former being included among our G3 up/amplified genes." (PMID 24866763, 2014). "For example, MYC can induce the accumulation of EZH2 in prostate cancer." (PMID 24261995, 2013). "MYC activation is thought to be an early event in prostate cancer." (PMID 24293458, 2013). "In prostate cancer biopsies, OGT is upregulated in association with MYC levels." (PMID 23964270, 2013). "A SNP upstream of MYC has been shown to affect the binding of transcription factor YY1 which may serve to regulate MYC expression in prostate cancers." (PMID 22950704, 2012). "Moreover, AhR is overexpressed in prostate cancer and cancer stem cells and it can bind to NF-κB and promote activation of MYC." (PMID 22215106, 2012). "With regard to its transcriptional regulation, a hypothetic role can be assigned to MYC, since recent gene expression profiling data revealed up-regulation of genes located on chromosome 8q, including MYC, in PDSS, and MYC has been reported to induce EZH2 in prostatic carcinoma." (PMID 23110793, 2012). "MYC ranks as one of the most consistently overexpressed genes comparing prostate tumours to normal prostate tissue in a meta-analysis of five data sets, indicating its importance in prostate cancer." (PMID 21814516, 2011). "Therefore, the regulation of these miRNAs by MYC occurs in both mouse and human prostatic cancer cells." (PMID 21941025, 2011). "Transient transfection of miR-26a and miR-26b mimics into 5 prostate cancer cell lines resulted in suppressed proliferation, indicating that these MYC targets of repression may have tumor-suppressive functions in the context of prostate cancer." (PMID 21941025, 2011). "To evaluate whether PI3K-pathway activation and MYC oncogene amplification co-occur in human prostate cancer, we examined oligonucleotide array CGH data from 194 prostate tumors, including 37 metastases." (PMID 21394210, 2011). "Yet, a number of observations suggest MYC may be involved in early phases of prostate cancer development as well." (PMID 20195545, 2010). "While these findings have been important for our understanding of the potential role of MYC in early human prostate cancer formation, additional studies are needed to address a number of enduring questions regarding MYC action in early prostate neoplasia and its relevance to the human disease." (PMID 20195545, 2010). "Another key question is whether changes in expression of a number of genes known to be relevant to prostate cancer may be explained, at least in part, by MYC overexpression." (PMID 20195545, 2010). "Also, we found a decrease in Nkx3.1 mRNA in Lo-MYC mice and an increase in Nkx3.1 mRNA levels in human prostate cancer cells (LNCaP) after siRNA induced MYC knockdown (C. Koh, AM De Marzo, unpublished observations)." (PMID 20195545, 2010). "Furthermore, microarray expression profiling studies defined a gene expression signature of MYC-induced prostate cancer in Hi-MYC mice that shares a number of features with human prostate cancer." (PMID 20195545, 2010).
prostate carcinoma (continued). "In this respect, it could be significant that DKC1 was recently identified as a direct target of MYC, a major regulator of cancer cell growth frequently overexpressed in aggressive breast and prostate cancers." (PMID 19755982, 2009). "These experiments demonstrate that SH-BC-893 reduces nuclear levels of prostate cancer drivers MYC and the AR by triggering PP2A-dependent proteasomal degradation and blocking KPNB1-mediated nuclear import in parallel, redundancy that could limit the development of drug resistance." (PMID 40588551, 2025). "Explore combination strategies that target OCT4 and other key master regulators—such as SOX2, MYC, EZH2, and BRN2—alongside immunotherapies, to more effectively disrupt the stemness and immune-evasive phenotypes associated with lineage plasticity in prostate cancer." (PMID 40722714, 2025). "One such example is the MYC gene, whose overexpression is responsible for many pathways important for tumourigenesis in several oncologic diseases, namely leukaemia, lung cancer, endometrial cancer, prostate cancer, glioma, and pancreatic ductal adenocarcinoma." (PMID 38542080, 2024). "Additionally, MYC gene overexpression is responsible for many pathways important for tumourigenesis in several oncologic diseases: leukaemia, lung cancer, endometrial cancer, prostate cancer, glioma, and pancreatic ductal adenocarcinoma." (PMID 38542080, 2024). "For instance, inhibiting PCAT-1 expression in CRC suppresses MYC mRNA expression, which may be explained by findings in prostate cancer where PCAT-1 regulates the binding between miR-34A and the 3 ‘untranslated region (UTR) of MYC mRNA, thus reducing its translation." (PMID 39075086, 2024). "In summary, this work elucidates NCAPD3 inhibits miR-30a-5p through two pathways: increasing STAT3-MALAT1 to sponge miR-30a-5p and increasing MYC to directly inhibit miR-30a-5p transcription, which could serve as potential therapeutic targets for prostate cancer." (PMID 38561330, 2024). "Therefore, elevated expression of BRD4 and MYC confer JQ1 resistance in prostate cancers." (PMID 37036970, 2023). "However, only c-MYC gene expression was significantly increased in prostate cancer tissues." (PMID 36776320, 2023). "As recently shown, prostate cancer-derived large extracellular vesicles (oncosomes) facilitated intercellular communication through inducing high MYC activity in stromal cells, and human medulloblastoma cells with MYC amplification could release extracellular vesicles carrying MYC sequences." (PMID 36140779, 2022). "Thus, we next sought to determine if MYC transcriptional activity status in low AR-A tumors could identify a more aggressive subtype of primary prostate cancer using the TCGA dataset." (PMID 35562350, 2022). "In prostate cancer models, PET imaging with the tracer 68Ga-citrate was shown to substitute the 89Zr-Tf PET imaging and some hints of the association of the signal with MYC deregulated cancers were provided, increasing the number of imaging modalities to annotate MYC." (PMID 34637026, 2021). "Consequently, in PHLPP2-positive MYC-driven advanced prostate cancer, it has been suggested that PHLPP2 may present a valuable therapeutic target." (PMID 32630372, 2020). "Besides that, EZH2 expression is positively correlated with MYC expression in prostate cancer." (PMID 33014831, 2020). "However, MYC is also reported to antagonize AR transcriptional activity in prostate cancer." (PMID 32630372, 2020). "Our findings showed first time showed that MYC is a direct target of curcumin in the context of both less aggressive and highly aggressive metastatic prostate cancer, further confirming the chemo-preventive and therapeutic potential curcumin in prostate cancer." (PMID 31581661, 2019).